POFUT2 (protein O-fucosyltransferase 2)
Description:
GDP-fucose protein O-fucosyltransferase involved in one of the two pathways responsible for protein O-linked fucosylation, a unique post-translational modification of cysteine-knotted proteins that regulates various biological functions. This pathway targets proteins with Thrombospondin type-1 (TSP1) repeats (TSR) in the endoplasmic reticulum. Catalyzes the reaction that attaches fucose through an O-glycosidic linkage to a conserved serine or threonine residue in the consensus sequence C1-X-X-S/T-C2 of thrombospondin type I repeats (TSRs) where C1 and C2 are the first and second cysteines of the repeat, respectively. O-fucosylates members of several protein families including the ADAMTS, the thrombospondin (TSP) and spondin families (Probable). Required for the proper secretion of ADAMTS family members such as ADAMTSL1 and ADAMTS13. The O-fucosylation of TSRs is also required for restricting epithelial to mesenchymal transition (EMT), maintaining the correct patterning of mesoderm and localization of the definite endoderm (By similarity).
Synonyms: C21orf80; FUT13; KIAA0958
Tractability: Small molecule: a structure with a bound ligand is known. Antibody: UniProt predicts a signal peptide or a membrane-spanning region. PROTAC: its protein half-life has been measured.
Gene: Protein-coding gene on chromosome 21 (45,263,928 to 45,287,898, reverse strand). Ensembl gene ENSG00000186866.
Subcellular location: Endoplasmic reticulum; Golgi apparatus
Pathways (Reactome):
Metabolism of proteins: O-glycosylation of TSR domain-containing proteins
Gene Ontology:
Molecular function: peptide-O-fucosyltransferase activity; fucosyltransferase activity
Biological process: positive regulation of protein folding; protein O-linked glycosylation via fucose; regulation of secretion
Cellular component: endoplasmic reticulum; Golgi apparatus; endoplasmic reticulum membrane
Genetic constraint (gnomAD): Loss-of-function variants: 23 observed, 45.42 expected, observed/expected ratio (o/e) 0.51, 90% interval 0.36 to 0.72. The upper end of that interval is the gene's LOEUF score, 0.72, which puts it in group 2 of 6, group 1 being the genes least tolerant of losing a copy. Missense variants: 492 observed, 527.99 expected, observed/expected ratio (o/e) 0.93, 90% interval 0.87 to 1. Synonymous variants: 256 observed, 218.19 expected, observed/expected ratio (o/e) 1.17, 90% interval 1.06 to 1.3.
Homologues: Orthologues: mouse Pofut2 (93% identical), rat Pofut2 (92% identical), chimpanzee POFUT2 (91% identical), dog POFUT2 (90% identical), macaque POFUT2 (90% identical), guinea pig POFUT2 (89% identical), tropical clawed frog pofut2 (78% identical), zebrafish pofut2 (73% identical), Caenorhabditis elegans pad-2 (44% identical), Drosophila melanogaster O-fut2 (38% identical).
Diseases named in the same sentence as POFUT2 in open-access papers:
POFUT2 is named in the same sentence as 12 diseases in open-access papers, as found by Europe PMC text mining. Sharing a sentence is not in itself a finding about the gene and the disease. The quoted sentences say what the papers report.
malaria (2 papers, 2017 to 2019). Malaria is a serious and sometimes fatal disease caused by a parasite that commonly infects a certain type of mosquito which feeds on humans. "To study the function of PoFUT2 in Plasmodium parasites, we knocked out this gene in the human malaria parasite P. falciparum." (PMID 31334132, 2019). "Genetic disruption of POFUT2 in Plasmodium falciparum results in ookinetes that are attenuated for colonizing the mosquito midgut, an essential step in malaria transmission." (PMID 28916755, 2017). "Here, we have generated PoFUT2 null-mutant P. falciparum and Plasmodium berghei (rodent) malaria parasites and, by phenotyping them throughout their complete life cycle, we show that PoFUT2 disruption does not affect the growth through the mosquito stages for both species." (PMID 31334132, 2019). "Therefore, POFUT2 plays a similar role in malaria parasites to that in metazoans: it ensures the trafficking of Plasmodium TSR proteins as part of a non-canonical glycosylation-dependent endoplasmic reticulum protein quality control mechanism." (PMID 28916755, 2017). "Therefore, in our hands PoFUT2 disruption did not affect oocyst development in the most relevant parasite-mosquito species combinations in a laboratory setting for both human and murine malaria models." (PMID 31334132, 2019).
breast carcinoma (1 paper, 2021). "We found that only FUT8, not FUT3, FUT11, POFUT1, or POFUT2, was closely and positively correlated with B7H3 in breast cancer tissues." (PMID 33976130, 2021).
colorectal cancer (1 paper, 2026). A primary or metastatic malignant neoplasm that affects the colon or rectum. "To investigate the mechanisms underlying POFUT2-mediated angiogenesis in colorectal cancer, we transfected HCT8 cells with a 3xFLAG-POFUT2 plasmid and employed a FLAG-tag antibody to immunoprecipitate POFUT2-interacting proteins for subsequent mass spectrometry analysis." (PMID 41583504, 2026). "Based on the immunohistochemical staining scores of POFUT2 in 20 colorectal cancer tissues, we categorized the samples into two groups: the high POFUT2 expression group (n=10) and the low POFUT2 expression group (n=10)." (PMID 41583504, 2026). "While our study has elucidated the molecular mechanism by which POFUT2 promotes angiogenesis in colorectal cancer through the regulation of JUP and VEGFA, several limitations should be acknowledged." (PMID 41583504, 2026). "We found that the increased expression of POFUT2 in colorectal cancer cells significantly promoted the angiogenic ability of HUVECS." (PMID 41583504, 2026).
colorectal tumours (1 paper, 2026). "Consistent with previous studies that report a significant increase in POFUT2 expression levels in patients with colorectal tumours, their findings suggest that POFUT2 may serve as a potential biomarker and therapeutic target for CRC26." (PMID 41583504, 2026).
Headache (1 paper, 2018). Cephalgia, or pain sensed in various parts of the head, not confined to the area of distribution of any nerve. "We identified numerous genes associated with headache, both temporal and other types: POFUT2 in CD4 cells, and SLC35F6, HTD2, ZNF708, KLRC4-KLRK1 and JMJD7 in CD8 cells." (PMID 30037347, 2018).
virus infection (1 paper, 2023). "The top 4 were “Cell matrix adhesion and organization” (COL6A1, COL6A2, COL18A1, JAM2, ADAMTS5 and POFUT2), “Immune/virus infection response” (MX1 and MX2), “Histone modification and chromatin remodeling” (NRIP1) and “Glycerolipid and lipid metabolism” (AGPAT3)." (PMID 38095646, 2023).
cancer (4 papers, 2015 to 2022). A tumor composed of atypical neoplastic, often pleomorphic cells that invade other tissues. "There is limited evidence on the role of this protein in cancer, but results of Pofut2 knockout mice showed that the loss of the protein leads to epithelial-mesenchymal transition in mouse embryogenesis, suggesting an important role of the protein in cancer." (PMID 26444668, 2015). "Meanwhile, POFUT1 and POFUT2 genes, involved in cancer-related pathways, have been screened." (PMID 36583106, 2022). "Lung-derived CD44low cells also exhibited upregulated levels of genes associated with mesenchymal cells and more dedifferentiated phenotypes in advanced cancers (e.g., FN1 and POFUT2)." (PMID 34579762, 2021).
infection (3 papers, 2017 to 2019). The state of being infected such as from the introduction of a foreign agent such as serum, vaccine, antigenic substance or organism. "To understand the importance of PoFUT2 for oocyst infection, we infected An. gambiae mosquitoes with PfWT and PfΔPoFUT2 gametocyte cultures." (PMID 31334132, 2019). "This indicates that POFUT2 is required for normal infection of the mosquito vector by P. falciparum ookinetes." (PMID 28916755, 2017). "This suggests that POFUT2 plays an important role in parasite transmission to mosquitoes and infection of the human host by ensuring trafficking of TSR proteins following glycosylation in the parasite ER." (PMID 28916755, 2017). "The recent functional characterization of P. falciparum PoFUT2 suggests a critical role of O-fucosylation during the infection of the mosquito host, although these results could not be replicated in an independent study." (PMID 31559936, 2019). "As reported, the ability to produce PoFUT2 null-mutant parasites demonstrates that the gene is not essential for asexual blood stage growth in culture or in a rodent model of infection." (PMID 31334132, 2019). "However, contrary to what has been described previously by others, P. berghei PoFUT2 null mutant sporozoites showed no deleterious motility phenotypes and successfully established blood stage infection in mice." (PMID 31334132, 2019).
POFUT2 also shares sentences with these, for which no sentence is quoted: acute myeloid leukemia (1 paper); adenocarcinoma (1); glioblastoma (1); lung carcinoma (1).